CYP2J2 (cytochrome P450 family 2 subfamily J member 2)
Diseases named in the same sentence as CYP2J2 in open-access papers (continued):
Sharing a sentence is not in itself a finding about the gene and the disease.
tumor (30 papers, 2012 to 2025). "To unravel the mechanism underlying the tumor-promoting effect of CYP2J2/EpOME in TNBC, we conducted a comprehensive transcriptomics analysis involving 106 disease cohorts and 52 control cohorts." (PMID 39695149, 2024). "Upregulation of let-7b suppressed the expression of CYP2J2 protein in cancerous tissues, which causes the inhibition of tumor phenotypes." (PMID 33312341, 2020). "Elevated EET levels in patients are linked to higher CYP2C and CYP2J2 mRNA and protein expression in tumor cells compared to adjacent normal cells." (PMID 32581794, 2020). "CYP2J2 protein levels were positively associated and sEH protein levels negatively associated with poorly differentiated tumor; as well, tumor sizes were greater and levels of alpha-fetoprotein were higher with high than low CYP2J2 level." (PMID 28030819, 2017). "Besides transcriptomics, we also used proteomics to further explore the mechanisms underlying the tumor-promoting effect of CYP2J2/EpOME." (PMID 39695149, 2024). "Thus, we speculate that the loss of function of CYP2J2 polymorphism, which detrimental to cardiovascular health, may decrease the risk of neoplastic disease." (PMID 33637672, 2021). "In CRC models, the predominant expression of CYP2W1, CYP2S1, CYP1B1, and CYP2J2 suggests their potential functional involvement in tumour metabolism, xenobiotic processing and disease progression." (PMID 41174467, 2025). "Increased Hcy levels promoted enhanced tumor cell characteristics, a phenomenon that was reversed in vitro by silencing CYP2J2." (PMID 40427612, 2025). "Protein levels of CYP2J2 were significantly higher in tumor tissues when compared with the controls." (PMID 39695149, 2024). "A metabolomics study identified that EpOMEs were significantly increased in the plasma of BC patients and MMTV-PyMT mice, which accounted for the upregulation of CYP2J2 in BC tumor tissues and tumor cells." (PMID 39695149, 2024). "To investigate the impact of CYP2J2/EpOME on lipid accumulation and adipocytes, we first performed hematoxylin and eosin (HE) staining on tumor tissues." (PMID 39695149, 2024). "Mechanistically, overexpression of CYP2J2 improves the prognosis of KIRC patients by regulating the immune microenvironment of the tumor." (PMID 34258261, 2021). "We found that, even though CYP2J2 expression levels were upregulated or downregulated in various tumor types, CYP2J2 expression levels only had significant correlations with the overall survival time (OS) and disease-free survival (DFS) of KIRC." (PMID 34258261, 2021). "The CYP2J2 expression was observed in most samples from all tumor types, including ESSC (20 of 31) and EAC (4 of 4)." (PMID 33659048, 2021). "Using the Oncomine database, which contained total unique analyses of 443 about CYP2J2, we detected diversities in CYP2J2 gene expression profiles between tumor and matched normal tissues." (PMID 34258261, 2021). "Further analyses revealed that the expression levels of the CYP2J2 transcript in KIRC tumor tissues were significantly higher compared to matched normal samples." (PMID 34258261, 2021). "CYP2J2, for example, is an isoform abundantly expressed in tumor tissues and metabolizes several antitumor tyrosine kinase inhibitors reducing their intracellular concentration." (PMID 32581794, 2020). "These strategies can be initiated with other P450s that have been identified in tumor cells, such as CYP2J2, CYP2W1, and CYP4Z1." (PMID 31998435, 2020). "Increased CYP2J2 expression.-Increased EET levels-Increased tumor grade-Increased tumor sizePotential therapy: dual-action sEH and COX-2 inhibitors showed increasing level of EETs and suppression of tumor growth in NDL/FVB mouse model." (PMID 32581794, 2020). "In some tumor tissues, CYP2J2 is upregulated, which forms EETs and increases tumor growth via the proangiogenic effect." (PMID 32182938, 2020). "For instance, CYP2W1, CYP1B1, CYP2C9, CYP2C8, CYP2J2, and CYP4A have been linked to tumor-specific expression." (PMID 31998435, 2020).
tumor (continued). "The levels of 4-epoxyeicosatrienoic acid (EET) isomers and their generative enzyme CYP2J2 level as well as intracellular Hcy level were higher in 42 cases of HCC than in paired non-tumor tissue." (PMID 28030819, 2017). "Vector-mediated overexpression of let-7b in tumor-engrafted mice led to the downregulation of CYP2J2 and significant reduction in tumor growth." (PMID 26583081, 2015). "Recently, Chen and colleagues have demonstrated that the expression of drug metabolizing enzyme cytochrome P450 epoxygenase 2J2 (CYP2J2) is inversely proportional to the tumor suppressor let-7b expression in squamous cell lung cancer." (PMID 26583081, 2015). "In HepG2 cell culture media, dasatinib is removed by all tumor-expressed CYP with the following clearance rate: CYP2J2>CYP1A1>CYP1B1." (PMID 24819355, 2014). "Despite the relatively low CYP2J2 prevalence, CYP2J2 protein expression is positively correlated with histological grade and tumor size, which is consistent with previous in vivo and in vitro studies." (PMID 25406731, 2014). "In the present study, we have shown a new mechanism for controlling the tumor-promotion function of CYP2J2." (PMID 22761738, 2012). "Their study of 42 HCC samples revealed significantly increased levels of 4-epoxyeicosatrienoic acid (EET) isomers, and the CYP2J2 enzyme responsible for their synthesis and intracellular Hcy were all significantly higher compared to corresponding non-tumor tissues." (PMID 40427612, 2025). "In addition, the expression of Cyp2j8 (homologous gene of human CYP2J2) was significantly up-regulated, whereas the expression of Cyp2j9, Cyp2c39, and Cyp2c40 was significantly down-regulated in the tumor tissues of MMTV-PyMT mice." (PMID 39695149, 2024). "One may concern that lipid accumulation play a role in the tumor-promoting effect of CYP2J2/EpOME in TNBC." (PMID 39695149, 2024). "Hence, a number of specific CYP2J2 inhibitors have been developed, and their efficacy in inhibiting tumor progression has been actively studied." (PMID 31998435, 2020). "Although overexpression of CYP2J2 has been shown to protect against anthracycline-induced cardiotoxicity in transgenic mice, CYP2J2-mediated EETs may promote tumor progression and metastasis." (PMID 33185690, 2020). "Interestingly, Wei's study showed that the CYP2C enzymes were correlated with Ki67 status, a measure of the number of cells that are actively dividing, while CYP2J2 levels were correlated with tumor grade and size." (PMID 32581794, 2020). "Overexpression of CYP2J2 and addition of synthetic EETs could enhance tumor growth via promoting angiogenesis." (PMID 33330047, 2020). "Finally, the expression of CYP2J2, which promotes tumor cell growth by converting arachidonic acid to epoxyeicosatrienoic acids, is also up-regulated in ETS− tumors." (PMID 30367117, 2019). "Furthermore, CYP2C8 and 2C9 protein levels positively correlated with Ki67 status, and CYP2J2 levels positively correlated with histological grade and tumor size." (PMID 25406731, 2014). "Furthermore, we recently found that Compound 26, the selective inhibitor of CYP2J2, significantly repressed the tumor-promotion function of CYP2J2." (PMID 22761738, 2012). "Our data suggest that the effect of CYP2J2-derived EETs on tumor formation was mediated by let-7b." (PMID 22761738, 2012). "Let-7b significantly inhibited the tumor phenotype by targeting CYP2J2." (PMID 22761738, 2012). "Furthermore, in a mouse model fed 2% (w/w) L-methionine, with or without folate deficiency, HHcy significantly promoted tumor growth and volume, and an increased CYP2J2 expression, along with DNA demethylation patterns." (PMID 40427612, 2025). "In addition, CYP2J2 has been associated with the occurrence and development of many tumor types; however, its role in KIRC pathogenesis has not been reported." (PMID 34258261, 2021).
tumor (continued). "CYP2J2 increased lung metastasis in mice xenograft models, independent of primary tumor size, while chemically inhibiting CYP2J2 activity, using compounds structurally related to terfenadine, significantly reduced the tumor cells' ability for adhesion and invasion." (PMID 32581794, 2020). "Finally, we aimed to investigate whether Hcy-mediated CYP2J2 might drive tumorigenesis in vivo by using a bioluminescence imaging system for sensitive detection of tumor growth in a mouse model of orthotopically induced HCC." (PMID 28030819, 2017). "Inhibition of the tumor-expressed metabolizing enzyme CYP2J2, could be a novel clinical strategy to improve TKI efficacy and to decrease the delay before relapse reflecting beta-lactamase inhibition that is a classical strategy to avoid antibiotic degradation and resistance." (PMID 24819355, 2014). "Besides MYC and RAS, let-7b can function as a tumor suppressor by blocking CYP2J2." (PMID 22761738, 2012). "Furthermore, let-7b may diminish cell proliferation and promote cell apoptosis of tumor cells via posttranscriptional repression of CYP2J2." (PMID 22761738, 2012). "Hence, the purpose of the present study was to investigate this hypothesis that let-7b might act as a tumor suppressor through targeting CYP2J2." (PMID 22761738, 2012). "Treatment with EpOMEs and overexpression of CYP2J2 to increase EpOMEs in TNBC cells significantly promoted cellular proliferation, migration, tumor growth, and metastasis." (PMID 39695149, 2024). "Collectively, our findings underscore the pivotal role of CYP2J2/EpOME in promoting the viability and proliferation of TNBC cells in vitro and tumor growth in vivo." (PMID 39695149, 2024). "Briefly, endothelial-specific expression of either CYP2C8 or CYP2J2 (Tie2-CYP2C8-Tr, Tie2-CYP2J2-Tr) accelerated the escape from tumor dormancy and extensive multi-organ metastasis." (PMID 33637672, 2021). "In addition, we reanalyzed the expression levels of the CYP2J2 gene and transcript in KIRC through UALCAN and found that their expression levels were significantly elevated in KIRC tumor tissues than in paracancerous normal samples." (PMID 34258261, 2021). "HER2+ tumor tissues are classified positive or weak positive/negative against CYP2J2 (33% positive and 45% weak positive/negative), and weak positive/negative against CYPC9/19 (40%)." (PMID 31072371, 2019). "Transcriptional upregulation of CYP2J2 and downregulation of sEH in HCC might explain the EET secretion and accumulation, related to the differentiation of tumor, tumor size and increased level of alpha-fetoprotein as well as intracellular Hcy level." (PMID 28030819, 2017). "CYP2J2) that are compatible with high intratumoral CYP activity and tumor-specific TKI degradation." (PMID 24819355, 2014). "Therefore, we speculated that the overexpression of CYP2J2 prolonged the survival outcome of KIRC patients, which may be related to the change of tumor immune microenvironment." (PMID 34258261, 2021). "The mRNA and protein levels of CYP2J2 were higher in tumor than non-tumor tissue, but sEH levels were less, which might promote the synthesis and prevent metabolization of EETs." (PMID 28030819, 2017). "However, only the expression of TXNIP, not CYP2J2 or GPC3, was positively correlated with the expression of circDCUN1D4 in LUAD tumor tissues, confirming that TXNIP is the target of circDCUN1D4." (PMID 33425493, 2021).
cardiovascular diseases (10 papers, 2010 to 2026). "CYP2J2 polymorphism has been studied mainly in cardiovascular diseases, with contradictory results among different ethnic groups." (PMID 31902555, 2020). "CYP2J2 polymorphism has been investigated in cardiovascular diseases, ischemic stroke, and Alzheimer's disease, and it has been shown to increase susceptibility to these diseases." (PMID 31902555, 2020). "In addition, studies linking CYP2J2 polymorphisms to the risk of developing cardiovascular disease (CVD) yielded contradictory results." (PMID 29966295, 2018). "One could suggest that the sex-dependant CYP2J2 mRNA expression explains higher susceptibility of men for the onset or progression of cardiovascular diseases." (PMID 21179487, 2010). "CYP2J2 and EETs have been repeatedly demonstrated to possess protective effects against various cardiovascular diseases." (PMID 37143707, 2023). "Human epidemiological studies also support a protective role of CYP2J2 against cardiovascular disease." (PMID 28328948, 2017). "Epidemiological studies suggest a protective role of CYP2J2 against cardiovascular disease in humans." (PMID 28328948, 2017). "CYP2J2 could metabolize arachidonic acid to four epoxyeicosatrienoic acids (EETs) (EETs: 5,6-, 8,9-, 11,12-, and 14,15-EET), which exerted diverse biological effects in cardiovascular diseases." (PMID 41602333, 2026).
cardiac disease (5 papers, 2018 to 2023). "Previous studies revealed that CYP2J2 plays an important role in the cardiovascular system and that CYP2J2 genetic polymorphisms are associated with the risk of cardiac disease." (PMID 37288113, 2023). "This is the first report demonstrating that cardiac disease alters EET levels in human ventricular heart tissue and is associated with differential expression of proteins involved in their formation and degradation including CYP2J2, POR, and sEH." (PMID 36293289, 2022). "We found that subjects with cardiac disease had lower CYP2J2 protein content than controls." (PMID 32210298, 2020).
retinopathy (1 paper, 2021). "In conclusions, CYP2J2 was found to inhibit the viability and angiogenesis of HRVECs by inhibiting Notch signaling in a hypoxia-induced retinopathy model." (PMID 34666595, 2021). "Next, we explored the regulatory roles of CYP2J2 in the Notch signaling pathway in our hypoxia-induced retinopathy model." (PMID 34666595, 2021). "Results from RT-qPCR and Western blotting revealed that DAPT promoted the effects of CYP2J2 on Notch signaling in hypoxia-induced retinopathy while EDTA reversed the inhibitory effect of CYP2J2 on Notch signaling in hypoxia-induced retinopathy." (PMID 34666595, 2021). "Having explored the relationship between Notch1 inhibition and CYP2J2, we next explored the mechanisms of a Notch1 agonist and CYP2J2 in hypoxia-induced retinopathy." (PMID 34666595, 2021). "CYP2J2 inhibits the viability and angiogenesis of retinal vascular endothelial cells via regulating the Notch signaling pathway in a hypoxia-induced retinopathy model." (PMID 34666595, 2021). "Together, these findings confirmed that CYP2J2 inhibits viability and angiogenesis of HRVECs in an in vitro model of hypoxia-induced retinopathy." (PMID 34666595, 2021). "Here, we aimed to explain the function and latent roles of Cytochrome P450 2J2 (CYP2J2) in hypoxia-induced retinopathy in retinal vascular endothelial cells (HRVECs)." (PMID 34666595, 2021). "Together, these findings suggest that EDTA reverses the inhibitory effect of CYP2J2 on the Notch signaling pathway in hypoxia-induced retinopathy." (PMID 34666595, 2021). "EDTA reverses the inhibitory effect of CYP2J2 on cell viability and migration in hypoxia-induced retinopathy." (PMID 34666595, 2021). "Effects of CYP2J2 on Dll4 and Jagged1 expression in hypoxia-induced retinopathy." (PMID 34666595, 2021). "Finally, we evaluated the effects of EDTA and CYP2J2 on cell viability and migration in hypoxia-induced retinopathy." (PMID 34666595, 2021). "CYP2J2 inhibits Notch signaling in an in vitro hypoxia-induced retinopathy model." (PMID 34666595, 2021). "The novel findings of our research are as follows: i) CYP2J2 inhibits HRVEC viability and angiogenesis in a hypoxia-induced retinopathy model; ii) the effects of CYP2J2 on hypoxia-induced HRVEC are regulated via the Notch signaling pathway." (PMID 34666595, 2021). "Our data revealed that up-regulation of CYP2J2 inhibited HRVEC viability, reduced the expression of PCNA, and inhibited migration; however, Terfenadone induced opposite effects on HRVEC viability and migration in hypoxia-induced retinopathy." (PMID 34666595, 2021). "CYP2J2 inhibits HRVEC viability and migration in hypoxia-induced retinopathy." (PMID 34666595, 2021). "Effects of CYP2J2 on HRVEC viability and migration in hypoxia-induced retinopathy." (PMID 34666595, 2021). "Further analysis using MTT and Transwell assays suggested that DAPT promotes the effects of CYP2J2 on cell viability and migration in hypoxia-induced retinopathy while EDTA reverses the inhibitory effect of CYP2J2 on cell viability and migration in hypoxia-induced retinopathy." (PMID 34666595, 2021).
CYP2J2 also shares sentences with these, for which no sentence is quoted: metabolic disease (3 papers); diabetic cardiomyopathy (2); gestational diabetes mellitus (2); maturity onset diabetes (2); pulmonary hypertension (2); bacterial infection (1); bladder cancers (1); breast tumor (1); cardiac arrhythmias (1); cerebrovascular disease (1); chronic asthma (1); coagulopathy (1); endometriosis (1); essential hypertension (1); gastrointestinal disease (1); hemorrhagic stroke (1); hyperhomocysteinemia (1); hyperlipidemia (1); hypertrophy (1); Impaired glucose tolerance (1); infarction (1); lung squamous cell cancer (1); lymphoma (1); melanoma (1); Nephropathy (1); non-alcoholic fatty liver disease (1); psoriasis vulgaris (1); renal carcinoma (1); renal fibrosis (1); sarcoma (1).
A further 4 diseases each share a sentence with CYP2J2 in 1 paper.